RN7SL517P (RNA, 7SL, cytoplasmic 517, pseudogene)
Gene: Miscellaneous RNA gene on chromosome 3 (43,314,951 to 43,315,255, forward strand). Ensembl gene ENSG00000241939.
Homologues: Orthologues: chimpanzee Metazoa_SRP (99% identical), macaque Metazoa_SRP (94% identical). Paralogues in human: RN7SL1 (79% identical), RN7SL122P (79% identical), RN7SL2 (79% identical), RN7SL3 (78% identical), RN7SL650P (78% identical), RN7SL126P (77% identical), RN7SL566P (77% identical), RN7SL97P (77% identical), RN7SL220P (77% identical), RN7SL187P (76% identical), RN7SL230P (76% identical), RN7SL322P (76% identical), and 700 more.